FGF2 (fibroblast growth factor 2)
Diseases named in the same sentence as FGF2 in open-access papers (continued):
Sharing a sentence is not in itself a finding about the gene and the disease.
gastric cancer (45 papers, 1996 to 2025). A primary or metastatic malignant neoplasm involving the stomach. "Treatment of macrophages and gastric cancer cells with recombinant IGFBP7 further showed that IGFBP7 promoted tissue-associated macrophages (TAM)/M2 polarization via FGF-2/Fibroblast Growth Factor Receptor 1 (FGFR-1)/Phosphoinositide 3-kinases (PI3K)/Protein kinase B (Akt) axis." (PMID 39045455, 2024). "As a member of the serine protease family, HTRA1 promotes the transformation of normal fibroblasts to CAFs in gastric cancer by activating NF-κB signaling to upregulate the expression of bFGF/FGF2." (PMID 39684264, 2024). "TGF-β signaling promoted the expression of IGFBP7 in CAFs, which in turn enhanced fibroblast growth factor-2 (FGF-2) expression in gastric cancer and resulted in increased macrophage infiltration and poor prognosis." (PMID 39045455, 2024). "It was also reported that PVT1 activates CD151 and FGF2 expression through suppression of miR-152 in gastric cancer." (PMID 36624401, 2023). "According to the studies, overexpression of HtrA1 can significantly increase bFGF/FGF2 secretion by gastric cancer cells by activating NF-кB signal." (PMID 34563186, 2021). "Fibroblast growth factor 2 (FGFR2) amplification, occurring in ~2–9% of gastric cancers (GC), is associated with poor overall survival." (PMID 28122360, 2017). "We used a defined serum-free medium consisting of EGF, FGF-2, B-27 supplement and N-2 supplement to maintain gastric cancer cell lines." (PMID 21394208, 2011). "We think that a deficit in PTX 3, which inhibits target cell activity by binding with high affinity to FGF2 in the gastric epithelium, thus preventing growth factor binding to receptors on the cell surface, prepares the foundation for gastric cancer development." (PMID 34048179, 2021). "The DDAHs association with FGF2 warrants further investigation as well, as DDAH2 has recently been shown to alleviate fibrosis associated with diabetic cardiomyopathy and DDAH1 to inhibit the Wnt/β-catenin pathway, EMT, and gastric cancer cell migration." (PMID 32121248, 2020). "Elevated receptor tyrosine kinases, such as epidermal growing factor receptor (EGFR), fibroblast growth factor 2 (FGF2), c-Kit, platelet-derived growth factor (PDGF), and its receptor (PDGFR), have been shown to affect the prognosis of gastric cancer patients." (PMID 36035313, 2022). "In gastric cancer cells, PVT1 was describes as acting as a sponge of miRNA-152, upregulating fibroblast growth factor 2 (FGF2), as in one of our proposed ceRNA axes." (PMID 35328496, 2022). "miR-152 suppresses the proliferation and motility of gastric cancer cells targeting CD151 and FGF2, which are cell surface receptors well-known to participate in the spreading, migration and invasion of tumors." (PMID 32083000, 2020). "In good agreement, PVT1 is negatively correlated with miR-152 expression in tumors from gastric cancer patients, and its genetic manipulation in SGC7901 and BGC823 gastric cell lines influences miR-152 levels and ultimately, CD151 and FGF2 expression." (PMID 32083000, 2020). "Because activated macrophages produce VEGF-A, IL-8, FGF-2, and PD-ECGF, MCP-1 expressed by gastric cancer cells plays a role in angiogenesis via recruitment and activation of macrophages." (PMID 20369064, 2010). "In addition, CAFs promote angiogenesis by producing fibroblast growth factor 2 (FGF2), and vascular endothelial growth factor A (VEGFA) in different cancers as well as galectin-1 expression in gastric cancer." (PMID 32264958, 2020). "The importance of FGF-2, PDGF-BB, and angiopoietin-2 for lymphatic metastasis of human gastric cancer is still unknown." (PMID 20369064, 2010). "TGF-β also prompts fibroblast growth factor 2 (FGF2) secretion in CAFs, which subsequently influences TAM polarization in gastric cancer (GC), significantly propelling migration, invasion and CSC traits." (PMID 39286635, 2024).
COVID-19 (39 papers, 2020 to 2026). A disease caused by infection with severe acute respiratory syndrome coronavirus 2. "In another study, authors found association between increased level of FGF2 and patients with severe COVID-19." (PMID 37053191, 2023). "The COVID-19 patients were detected with elevated FGF-2 in serum, which was closely associated with severe COVID-19 and ICU admission." (PMID 35350754, 2022). "This pattern, along with delayed elevations in FGF-2 levels, has been observed in individuals who develop post-COVID-19 pulmonary fibrosis." (PMID 40872813, 2025). "In a study involving 294 COVID-19 patients, the analysis revealed key post-COVID cytokines—FGF-2, VEGF-A, EGF, IL-12(p70), IL-13, and IL-6—crucial for understanding pathophysiology." (PMID 38793604, 2024). "In our study, COVID-19 recovering individuals with different degrees of microbial dysbiosis exhibited persistent inflammatory signaling of FGF2, MCP-1, IL-6, and IFN-γ." (PMID 38172612, 2024). "This aligns with a study showing increased lung blood vessel growth in fatal COVID-19 cases correlated with upregulated FGF2 gene expression." (PMID 38568894, 2024). "In contrast, FGF-2 expression was found to be upregulated in lungs in patients who died from COVID-19." (PMID 36012146, 2022). "The elevated levels of TNF α, IL-1RA, IL-6, IL-8, IL-10, IP-10, G-CSF and FGF-2 in both patient groups with COVID-19 in our study coincided with previously published studies." (PMID 36012146, 2022). "Several investigators found elevated plasma levels of placental growth factor (PlGF) and fibroblast growth factor-2 (FGF-2) in sera from COVID-19 patients correlated with disease severity." (PMID 36140343, 2022). "Symptomatic COVID-19 patients, in comparison to asymptomatic/mild individuals, had only FGF-2 elevated." (PMID 35844615, 2022). "Plasma concentrations of FGF2 and stem cell factor, required for lung repair, were also decreased in patients with COVID-19." (PMID 34648357, 2021). "In addition, several studies demonstrated the positive correlation between FGF2 and angiotensin, suggesting a small regulatory circuit that involves miR-936–ACE2–FGF2 in COVID-19 and male infertility." (PMID 34204705, 2021). "In severe COVID-19, FGF2 level showed small fluctuations between 1 and 20 dpi, and then rapidly increased after 21 dpi, which might be responsible for SARS-CoV-2-triggered renal damage as well." (PMID 34103487, 2021). "Elevations in the EGF, FGF2, VEGFA, sVEGFR1, sVEGFR2, sVEGFR3, PDGFAA, PDGFABBB and sEGFR repair factors have been observed in patients with COVID-19." (PMID 36142255, 2022). "The lower serum levels of the repair factor FGF2 and the higher levels of PDGFABBB, EGF and PDGFAA had significant predictive value for a good prognosis in severe COVID-19 patients." (PMID 36142255, 2022). "The most striking feature of liver failure was the elevation of CCL23, FGF2, and KRLD1 and depression of KIR3DL1 at admission, while Gal-1 and DCN were decreased later during the history of COVID-19." (PMID 34177897, 2021). "Significantly up-regulated levels of cytokines and chemokines including IL1-β, IL1RA, IL10, IL9, IL8, IL7, basic FGF2, GCSF, GMCSF, IFNγ, IP10, MCP1, MIP1α, MIP1β, PDGFB, TNFα, and VEGFA in blood, have been confirmed in COVID-19 patients." (PMID 33041797, 2020). "This information emphasizes the detrimental impact that high levels of FGF-2 and VEGF-A could have on the respiratory function of COVID-19 patients." (PMID 38568894, 2024).
COVID-19 (continued). "MiRNAs that were downregulated in serum of COVID-19 patients mainly target genes promoting angiogenesis (e.g., VEGFA, ANGPT2, COL4A1, FGF2, ZEB1), apoptosis, autophagy, stress response (e.g., ATG12, ATG14, ATG2B, SOD2, TXNIP), and inflammation (e.g., CXCL9, CXCL10, IL1R1, TNF)." (PMID 36032130, 2022). "Similarly, FGF-2, FLT-3L, IL-9, IL-17E/IL-25, IP-10, MCP-3, and MIP-1β were also positively correlated with SOFA scores in COVID-19 patients." (PMID 34131192, 2021). "Only nine of these cytokines were shared between the two profiles Furthermore, the salivary hepatocyte growth factor (HGF) and fibroblast growth factor 2 were statistically significantly lower in COVID-19-positive patients compared to the controls (<0.05) but not in blood." (PMID 38617584, 2024). "Moreover, in our cohort group, IL-1β, IL-7 and FGF-2 elevated in samples from patients with severe, but not with moderate COVID-19 compared to HDs." (PMID 36012146, 2022). "Our research showed a significant reduction in VEGF, FGF-2 and PDGF levels in patients with OA, who had COVID-19 and those who did not have a history of SARS-CoV-2 infection." (PMID 37484856, 2023). "Thus, in patients with OA who did not suffer from COVID-19, established a decrease in the levels of VEGF by 34.3%, FGF-2 by 26.2% and PDGF by 39.7%, compared to healthy control (p ≤ 0.001)." (PMID 37484856, 2023).
Obesity (39 papers, 2012 to 2026). Accumulation of substantial excess body fat. "FGF2 is increased in the context of obesity, and increased sera levels have been associated with endocrine-resistant breast cancer." (PMID 33019728, 2020). "In this manuscript, we used growth in ultra-low attachment conditions to develop a novel phenotypic transformation HTS assay using FGF2/FGFR1 signaling as the target-based mechanism to identify chemopreventive agents for obesity-associated epithelial cancers." (PMID 31311976, 2019). "This study aimed to investigate the associations of both the plasma FGF2 levels and SNPs in FGF2 gene with obesity phenotypes in Han Chinese populations." (PMID 26879180, 2016). "We selected 11 SNPs in FGF2 to test for associations with obesity-related traits (BMI, fat mass and WHRadjBMI) in the discovery sample of 1,300 Han Chinese subjects." (PMID 26879180, 2016). "FGF2 was linked to obesity and elevated resistance to anti-VEGF therapy in a preclinical study." (PMID 37800138, 2023). "Additionally, disrupting FGF2 increased the thermogenic capacity of brown and beige fat and FGF2 loss protected mice from high-fat-induced obesity and hepatic steatosis." (PMID 35625102, 2022). "Previous studies have implicated FGF2 in the obesity–cancer axis, as VAT levels of FGF2 were positively correlated with the capacity of VAT to stimulate mammary and skin epithelial cell growth, and circulating FGF2 levels were associated with overall adipose tissue mass in humans." (PMID 34685650, 2021). "Therefore, the FGF2/FGFR1 signaling axis is a potential chemopreventive target for obesity-associated epithelial cancers." (PMID 31311976, 2019). "eQTL analyses revealed that SNPs associated with obesity also affected FGF2 expression." (PMID 26879180, 2016). "Given the limited evidence of association study for human FGF2 gene with obesity, we investigated whether the common variants in FGF2 were associated with obesity phenotypes, including BMI, fat mass and WHRadjBMI." (PMID 26879180, 2016). "Our findings suggested that high plasma FGF2 level correlated with increased risk of obesity, and FGF2 gene polymorphisms could affect individual variances of obesity in Han Chinese population." (PMID 26879180, 2016). "Our results suggest that FGF2 could be a novel candidate for obesity by processing a series of association tests and referring to its biological functions." (PMID 26879180, 2016). "Taking into account of all those biological evidence and our statistical findings, we suggested that FGF2 gene could have potential impact on human fat mass regulation, and high plasma FGF2 level might lead to the increased risk of obesity." (PMID 26879180, 2016). "To test the hypothesis, firstly, we performed association tests to determine whether plasma FGF2 was correlated with obesity." (PMID 26879180, 2016). "However, all of these significant evidences, combined with our findings, support FGF2 as an obesity-associated gene in humans." (PMID 26879180, 2016). "Then, we hypothesized that association might also exist between the SNPs in FGF2 gene and obesity traits." (PMID 26879180, 2016). "Enhanced expression of FGF2 in the adipose tissues by BMP-9 injection might underlie the mechanism by which BMP-9 suppressed high fat diet-induced obesity." (PMID 25790378, 2015). "In conclusion, evidence from genetic ablation and exogenous treatment in in vitro models ofadipocytes demonstrate, for the first time, that shed Sdc4 from adipocytes during obesity acts as a novel suppressor of lipolysis through the FGF2/FGFR1 axis." (PMID 40180176, 2025). "Linagliptin, another DPP4 inhibitor, was suggested to have a cardioprotective role through FGF-2/EGR-1 pathway in mice with dietary obesity, and capillary rarefaction was suggested to be important in this process." (PMID 41463358, 2025). "The stimulatory concentration of FGF2 on growth in soft agar (>0.1 ng/mL) is similar to what has been reported for physiological serum concentrations in obesity." (PMID 34685650, 2021).
Obesity (continued). "The Fibroblast Growth Factor 2 (FGF2) is elevated in the context of obesity, the disruption of which leads to an increase of thermogenesis with higher energy expenditure and stable lipid maintenance." (PMID 34889899, 2021). "The crucial genes of aquaporin 8a (aqp8), mucin 2.1 (muc2.1), fibroblast growth factor 2 (fgf2), and proopiomelanocortin a (pomca) can indicate the intestinal secretory and absorptive-, and obesity-related functional abnormality in the host." (PMID 34675901, 2021). "MCF-10A cells were treated with 50 ng/mL of leptin and/or 5 ng/mL of FGF2 to simulate the physiologic circulating concentrations of these growth factors in obesity." (PMID 33019728, 2020). "We performed correlation analyses of plasma FGF2 levels with obesity phenotypes, including BMI and body fat mass, in 62 unrelated Han Chinese subjects." (PMID 26879180, 2016). "Considering the limited findings, the level of FGF2 and genetic basis in obesity still remain poorly understood." (PMID 26879180, 2016). "However, the association of FGF2 polymorphisms and obesity remains unclear." (PMID 26879180, 2016). "Expression levels of FGF2 in fat tissues from normal and obese mice were also analyzed to determine the relationship between high fat diet-induced obesity and expression levels of FGF2 in fat tissues." (PMID 25790378, 2015). "In order to analyze relationship between FGF2 expression patterns and high fat diet-induced obesity, FGF2 mRNA expression levels in the epididymis adipose tissues from mice fed with normal chow diet or high fat diet were determined." (PMID 25790378, 2015). "Furthermore, studies have shown that pre-gravid obesity also influences the levels of granulocyte-macrophage colony-stimulating factor (GM-CSF) and fibroblast growth factor 2 (FGF-2)." (PMID 37515062, 2023). "Importantly, the expression levels of intestinal secretory and absorptive genes (aqp8 and muc2.1), and obesity-related genes (fgf2 and pomca) were significantly up-regulated in the DEHP exposed groups." (PMID 34675901, 2021). "As circulating FGF2 levels correlate with adipose tissue mass in humans, FGF2/FGFR1 signaling could be a potential mechanism in which obesity influences the mammary gland." (PMID 33019728, 2020). "Given that the major definition of obesity is the excessive proliferation of adipocytes, it reminds us that FGF2 might be related with obesity and FGF2 gene could be a new candidate gene for obesity." (PMID 26879180, 2016). "We found that plasma FGF2 levels were positively correlated with fat mass, and marginally correlated with BMI in the same direction, suggesting that FGF2 might play a positive role in obesity." (PMID 26879180, 2016). "Therefore, the aims of this study were as follows: 1) to evaluate the associations of plasma FGF2 levels with obese status and 2) to investigate the relationship of SNPs in FGF2 with obesity related traits in Han Chinese populations." (PMID 26879180, 2016). "BMP-9, which has been reported to enhance brown adipogenesis and suppress obesity, may counteract the high fat diet-mediated suppression of FGF2 expression in the epididymal adipocytes." (PMID 25790378, 2015). "Additionally, an inhibitor of FGF2 has been shown to prevent obesity and hepatic steatosis." (PMID 41602630, 2026). "It implies that the inhibitors of VEGFA and FGF2 might be potential ligands against obesity." (PMID 34889899, 2021). "Strikingly, ob-dT bASCs already displayed an enhanced gene expression of CXCL2, CXCL1, CXCL3, FGF2 and CCL2, compared to ln-dT bASCs, suggesting a crucial impact of obesity on bASCs." (PMID 36710348, 2023). "The expression of another angiogenic factor, fibroblast growth factor-2 (FGF-2), is increased during adipocyte differentiation and during the induction of obesity by high-fat diet in mice." (PMID 33633579, 2020).
Obesity (continued). "Our present results also suggested that DPP-4 inhibits FGF-2/EGR-1/VEGF-A signaling to promote cardiac capillary rarefaction and cardiac dysfunction in mice with dietary obesity." (PMID 28771625, 2017). "Since we previously reported that intraperitoneal injection of BMP-9 (200 μg/kg/wk) suppressed high fat diet-induced obesity, we also determined if BMP-9 injection changed expression levels of FGF2 in the adipose tissues." (PMID 25790378, 2015). "Pre-adipocytes secrete basic fibroblast growth factor (bFGF/FGF-2), involved in promoting vascular endothelial cell growth, levels of which are increased with obesity." (PMID 23675368, 2013). "Subsequently, the shed-Sdc4-induced FGF2/FGFR1 activation inhibits adipocyte lipolysis by suppressing HSL phosphorylation, which uncovered a specific mechanism of shed Sdc4 in the development of obesity." (PMID 40180176, 2025). "Notably, FGF2 and to a lesser extent, FGF1, were each more highly expressed in CAFs compared to distant fibroblasts, but the distant fibroblasts from women with obesity had greater FGF2 expression than the lean group." (PMID 37800138, 2023). "The observed alterations in FGF-2, FGF-19, FGF-22, and FGF-23 concentrations—particularly their associations with hypertension, obesity, nephropathy, and joint degeneration—support their role not only in the pathogenesis but also in the clinical stratification of diabetic complications." (PMID 40943671, 2025).